FOXRED2 (FAD dependent oxidoreductase domain containing 2)
Description:
Probable flavoprotein which may function in endoplasmic reticulum associated degradation (ERAD). May bind non-native proteins in the endoplasmic reticulum and target them to the ubiquitination machinery for subsequent degradation.
Synonyms: ERFAD; FLJ23322
Tractability: Antibody: UniProt predicts a signal peptide or a membrane-spanning region. PROTAC: ubiquitination databases record sites on it; its protein half-life has been measured.
Gene: Protein-coding gene on chromosome 22 (36,487,190 to 36,507,221, reverse strand). Ensembl gene ENSG00000100350.
Subcellular location: Endoplasmic reticulum lumen
Gene Ontology:
Molecular function: flavin adenine dinucleotide binding; protein binding
Biological process: ERAD pathway
Cellular component: endoplasmic reticulum lumen
Genetic constraint (gnomAD): Loss-of-function variants: 32 observed, 53.88 expected, observed/expected ratio (o/e) 0.59, 90% interval 0.45 to 0.8. The upper end of that interval is the gene's LOEUF score, 0.8, which puts it in group 3 of 6, group 1 being the genes least tolerant of losing a copy. Missense variants: 848 observed, 959.53 expected, observed/expected ratio (o/e) 0.88, 90% interval 0.83 to 0.94. Synonymous variants: 405 observed, 409.87 expected, observed/expected ratio (o/e) 0.99, 90% interval 0.91 to 1.07.
Homologues: Orthologues: chimpanzee FOXRED2 (99% identical), dog FOXRED2 (87% identical), macaque FOXRED2 (87% identical), guinea pig FOXRED2 (87% identical), pig FOXRED2 (86% identical), rat Foxred2 (83% identical), mouse Foxred2 (82% identical), rabbit FOXRED2 (78% identical), tropical clawed frog foxred2 (61% identical), zebrafish foxred2 (52% identical), Caenorhabditis elegans fmo-3 (14% identical), Caenorhabditis elegans fmo-1 (13% identical), and 3 more. Paralogues in human: FMO3 (17% identical), FMO4 (16% identical), FMO1 (15% identical), FMO2 (15% identical), FMO5 (15% identical).
Diseases named in the same sentence as FOXRED2 in open-access papers:
FOXRED2 is named in the same sentence as 3 diseases in open-access papers, as found by Europe PMC text mining. Sharing a sentence is not in itself a finding about the gene and the disease. The quoted sentences say what the papers report.
breast carcinoma (1 paper, 2023). "For example, we confirmed by qPCR that the overexpression of FOXRED2 in breast cancer cells was due to the overexpression of noncanonical transcripts rather than the canonical transcripts." (PMID 37741908, 2023).
diabetes (1 paper, 2024). "We used machine learning to identify six key genes closely associated with vascular aging in diabetes: TFB1M, FOXRED2, LY75, DALRD3, PI4K2B, and NDOR1." (PMID 38809515, 2024). "Using bioinformatics and machine learning techniques, we identified six key genes that are closely associated with vascular aging in diabetes: TFB1M, FOXRED2, LY75, DALRD3, PI4K2B, and NDOR1." (PMID 38809515, 2024). "The expression of TFB1M, FOXRED2, DALRD3, PI4K2B, and NDOR1 was negatively correlated with vascular aging in diabetes, while LY75 expression was positively correlated." (PMID 38809515, 2024). "However, there is currently no direct evidence of the effect of FOXRED2 on vascular aging in diabetes." (PMID 38809515, 2024).
cancer (2 papers, 2015 to 2023). A tumor composed of atypical neoplastic, often pleomorphic cells that invade other tissues. "The function of FOXRED2 in cancer is not yet fully understood, and further studies are required to investigate its role in chronic ATLL." (PMID 36978083, 2023).